BHLHE41 (basic helix-loop-helix family member e41)
Diseases named in the same sentence as BHLHE41 in open-access papers (continued):
Sharing a sentence is not in itself a finding about the gene and the disease.
Autoimmunity (1 paper, 2022). The occurrence of an immune reaction against the organism's own cells or tissues. "Our data suggest that a subset of innate B-1 cells, identified by classical markers (Bhlhe41, Cd43, and IgM) and context-specific markers (Cxcr3 and Itgb1), can contribute to autoimmunity in BOS, and thus represent potential therapeutic value." (PMID 36134664, 2022).
bladder cancer (1 paper, 2024). "In this study, we found that BHLHE41 was lowly expressed in bladder cancer tissues and cell lines, and lower expression of BHLHE41 was associated with poor overall survival in bladder cancer patients." (PMID 38811952, 2024). "Collectively, these findings further supported that overexpression of BHLHE41 inhibited bladder cancer growth in vivo, which might be associated with the downregulation of PYCR1 and the inactivation of PI3K/AKT signaling pathway." (PMID 38811952, 2024). "Our investigation revealed that the expression of BHLHE41 was significantly downregulated in both bladder cancer tissues and cell lines." (PMID 38811952, 2024). "In this work, our team discovered for the first time that BHLHE41 was downregulated in bladder cancer tissues and cells, and had a favorable correlation with a good prognosis in bladder cancer patients." (PMID 38811952, 2024). "In this study, we first revealed that BHLHE41 functions as a tumor suppressor, effectively impeding the progression of bladder cancer." (PMID 38811952, 2024). "In summary, we examined the expression level and the role of BHLHE41 in bladder cancer, and identified that BHLHE41 inhibited bladder cancer progression via regulation of PYCR1 stability and thus inactivating of PI3K/AKT signaling pathway." (PMID 38811952, 2024). "To examine the functional roles of BHLHE41 in bladder cancer, we established the stable BHLHE41-overexpressing BCa cells through lentivirus infection, the efficiency of which was demonstrated via western blot and qRT-PCR assays." (PMID 38811952, 2024). "We discovered that BHLHE41 is a tumor suppressor in bladder cancer and conducted in vitro and in vivo investigations to show its influence on cell proliferation, migration, invasion, and cell cycle progression." (PMID 38811952, 2024). "Consistent with the results in dataset, the mRNA and protein levels of BHLHE41 were lower in bladder cancer tissues than that in adjacent normal tissues, as validated by qRT-PCR, and western blot tests." (PMID 38811952, 2024). "Collectively, these findings indicated that BHLHE41 was downregulated in bladder cancer and negatively correlated with patients’ prognosis." (PMID 38811952, 2024). "BHLHE41 played a suppressive role in the progression of bladder cancer via regulation of PYCR1 stability and thus inactivation of PI3K/AKT signaling pathway." (PMID 38811952, 2024). "This suggests that BHLHE41 plays a crucial role in suppressing the development of bladder cancer." (PMID 38811952, 2024). "The BHLHE41/PYCR1/PI3K/AKT axis might be a potential therapeutic target for bladder cancer intervention." (PMID 38811952, 2024). "Furthermore, our study revealed that the overexpression or suppression of BHLHE41 may effectively hinder or enhance the proliferation, migration, and invasion of bladder cancer cells." (PMID 38811952, 2024). "BHLHE41 might be a useful prognostic biomarker and a tumor suppressor in bladder cancer." (PMID 38811952, 2024). "Our findings demonstrated that upregulation or downregulation of BHLHE41 resulted in a reduction or rise in the phosphorylation level of PI3K and AKT, suggesting that BHLHE41 has a negative regulatory effect on the PI3K/AKT signaling pathway in bladder cancer." (PMID 38811952, 2024).
cholesteatoma (1 paper, 2022). A pathologic process characterized by the proliferation of keratinizing squamous epithelium resulting in the accumulation of keratin and cells in the middle ear and/or mastoid. "However, in our own middle ear expression dataset from the same patients, all 12 genes were DEGs for cholesteatoma: RTN4, RAB5A, CRYBG1, RGS22, HEPHL1, and SPTLC3 were upregulated, while APBB1IP, BHLHE41, ARID3A, C5AR1, CPT1B, and FAM227A were downregulated." (PMID 36699445, 2022).
Cognitive impairment (1 paper, 2024). Abnormal cognition is characterized by deficits in thinking, reasoning, or remembering. "Consistently, we also found an increase in Bhlhe41 expression in hippocampal neurons under high-glucose conditions, and this increase led to cognitive impairment in both type 1 and type 2 diabetic mice." (PMID 39375536, 2024).
demyelination (1 paper, 2026). "Bhlhe41- or Aurka-deficient young mice exhibited aging-like microglial morphology, phagocytic deficits, progressive CD22 upregulation, and remyelination impairment in cuprizone-induced demyelination model." (PMID 41896238, 2026).
lung squamous cell carcinoma (1 paper, 2021). "We analyzed BHLHE41 function via in silico and immunohistochemical studies of 177 surgically resected non-small cell lung cancer (NSCLC) samples and 18 early lung squamous cell carcinoma (LUSC) cases." (PMID 34768959, 2021). "BHLHE41 expression was significantly higher in normal lung than in LUAD and lung squamous cell carcinoma (LUSC) (p = 1.74 × 10−11 and p = 1.47 × 10−7, respectively)." (PMID 34768959, 2021).
nicotine dependence (1 paper, 2025). Physical and psychological dependence on nicotine. "Previous reports indicated that SLC2A13, BHLHE41, VGF and AHR variants are associated with heavy and problem drinking in patients as well as with nicotine dependence in tobacco users." (PMID 39880903, 2025).
renal clear-cell carcinoma (1 paper, 2021). "In contrast, BHLHE41 was reported to be related to tumor progression in MLL-AF6-positive AML and renal clear-cell carcinoma." (PMID 34768959, 2021).
Salmonella Infections (1 paper, 2021). Infections with bacteria of the genus SALMONELLA. "Many of these genes (e.g. Lhfpl2, Bhlhe41, Hyal1, and Tbc1d2) have previously been reported as differentially expressed in M1 vs. M2 macrophages and their downregulation likely represents M1 polarization that occurs following Salmonella infection." (PMID 34305890, 2021).
situ adenocarcinoma (1 paper, 2023). "Immunohistochemical studies showed that BHLHE41/DEC2 expression is almost exclusively limited to the lepidic growth part of LUAD, in situ adenocarcinoma, very early LUSC cells, and normal lung epithelial cells." (PMID 37511489, 2023).
squamous cell carcinoma (1 paper, 2021). A carcinoma arising from squamous epithelial cells. "Only 2 out of 45 (4.4%) non-LUAD tumors, including 43 squamous cell carcinomas and 2 pleomorphic carcinomas, showed positive staining, and the remaining cancers did not express BHLHE41." (PMID 34768959, 2021).
temporal lobe epilepsy (1 paper, 2025). A localization-related (focal) form of epilepsy characterized by recurrent seizures that arise from foci within the temporal lobe, most commonly from its mesial aspect. "In this study, we employed weighted gene co‐expression network analysis (WGCNA) to identify the basic helix‐loop‐helix (bHLH) family member e41 (BHLHE41, also known as DEC2) as a critical regulator of intrinsic and synaptic neuronal plasticity in temporal lobe epilepsy (TLE)." (PMID 40641288, 2025).
Waldenstrom macroglobulinemia (1 paper, 2021). "The expression of BHLHE41 is reported to be upregulated in patients with Waldenstrom macroglobulinemia, and might be associated with poor prognosis in NDMM." (PMID 33544757, 2021).
tumor (61 papers, 2011 to 2026). "Pharmacological inhibition of the MAPK/JNK signaling pathway rescued the impaired tumor cell invasiveness caused by BHLHE41 knockdown, suggesting that BHLHE41 primarily promotes MCF-7 cell invasion via activation of the MAPK/JNK axis." (PMID 40508038, 2025). "Research conducted by Liu, Zhang and their colleagues has demonstrated that BHLHE41 plays a regulatory role in the activity of tumor-associated immune cells, thereby influencing the host immune system’s ability to recognize and eliminate tumors." (PMID 39590319, 2024). "The study results showed that the reduction in expression levels of all four investigated genes, CA9, NDUFA4L2, EGLN3, and BHLHE41, is associated with tumor metastasis." (PMID 37443682, 2023). "Rs7132434, located on chr 12, has been characterized as a functional variant that alters AP-1 binding leading to upregulation of BHLHE41, thus promoting tumor growth through induction of IL-1163." (PMID 36681680, 2023). "The top GRNs in primary tumors were TCF4, TAGLN2, FOXK1, and BHLHE41, whereas the top upregulated GRNs in recurrent tumor cells were FOXP2, FOXD1, SIX4, and HMGB1." (PMID 39711559, 2024). "The regulon specificity score (RSS) highlighted unique regulons across the three studied regions, with MITF(+), PRDM1(+), MAX(+), TFEC(+), and BHLHE41(+) emerging as the most specific regulons within the tumor core." (PMID 38938448, 2024). "In TNBC, BHLHE41/DEC2 is a crucial tumor-suppressing molecule, since it can inhibit HIF-1 and possibly XBP1 functions and cancer stem cells." (PMID 37511489, 2023). "Previously, BHLHE41/DEC2 has been reported to function as a tumor suppressor by downregulation of cyclin D in NSCLS." (PMID 37511489, 2023). "At the same time, increased expression of BHLHE41 can inhibit tumor development by suppressing invasion, as it is demonstrated in various types of cancer." (PMID 37443682, 2023). "This is similar to previous results that BHLHE41 overexpression inhibits tumor growth and metastasis, as well as being positive for the EMT regulator E-cadherin." (PMID 35615737, 2022). "It was found that BHLHE41 overexpression significantly reduced tumor volume and tumor weight and promoted the positive expression of BHLHE41 in tumor tissues." (PMID 35615737, 2022). "In this study, CC tumor xenografts in nude mice were performed to explore the effect of BHLHE41 overexpression in reducing hypoxia-induced malignant behavior of CC cells." (PMID 35615737, 2022). "From these previous studies, BHLHE41 can work as both a tumor promoter and suppressor, depending on the cellular context." (PMID 34768959, 2021). "Our results show that in ccRCC tumors, the initial increase in expression of BHLHE41 decreases as the tumor stage progresses, which meets the needs of ccRCC development i.e., the nature of its effect on the tumor changes as it develops." (PMID 34046336, 2021). "Although increased expression of BHLHE41 stimulates the proliferation of tumor cells, which is especially important for tumor growth at the initial stage of development, it also inhibits its further development." (PMID 34046336, 2021). "On the contrary, the expression of PER2, PER3, CRY1, KIAA1737, and BHLHE41 are negatively correlated with the infiltration level of four tumor‐infiltrating lymphocytes in pan‐cancer." (PMID 31927791, 2020). "Increased expression of BHLHE41 stimulated the proliferation of tumor cells of ccRCC, and a knockdown led to a significant decrease in this feature." (PMID 31936274, 2020). "A number of studies have indicated a role for BHLHE41 in tumor development, though in different settings, different effects have been observed." (PMID 28715484, 2017). "As has been previously reported, we observed an effect of RCC-associated polymorphisms (including rs12814794) at this locus on the expression of BHLHE41 mRNA in ccRCC tumor samples analyzed by The Cancer Genome Atlas (TCGA)." (PMID 28715484, 2017).
tumor (continued). "Evidence from the cancer microarray database, ONCOMINE35, 36, revealed microarray gene-expression studies showing higher expression of BHLHE41 in RCC tumours compared with adjacent normal kidney tissue, in the range of 7–29-fold more expression." (PMID 27384883, 2016). "We separated the expression data matrix in the TCGA-BLCA dataset into BHLHE41high and BHLHE41low groups based on the median expression level of BHLHE41 and then performed bioinformatic analysis to evaluate the potential mechanisms of tumor inhibition mediated by BHLHE41." (PMID 38811952, 2024). "Finally, to evaluate the anti-tumor effect of BHLHE41 overexpressing in vivo, equal amounts of LV-BHLHE41 and LV-Ctrl T24 cells were subcutaneously injected into the BALB/c nude mice." (PMID 38811952, 2024). "BHLHE41/DEC2 has been reported to act as a tumor suppressor in several types of cancers." (PMID 37511489, 2023). "BHLHE41/DEC2 expression also suppressed HCT116 xenograft tumor growth." (PMID 37511489, 2023). "Therefore, increased expression of BHLHE41 can enhance the proliferative properties of tumor cells at the early stage of ccRCC." (PMID 37443682, 2023). "This sounds paradoxical; however, BHLHE41/DEC2 is a tumor-suppressive and oncogenic molecule." (PMID 37511489, 2023). "In addition, it was found that in animal experiments, overexpression of BHLHE41 can also reduce the volume and mass of tumor mice." (PMID 35615737, 2022). "Moreover, BHLHE41 overexpression reduced tumor volume, weight, and EMT-related proteins levels in tumor tissues." (PMID 35615737, 2022). "Consequently, the expression of CA9, NDUFA4L2, EGLN3, BHLHE41, VWF, IGFBP3, and ANGPTL4 is associated with ccRCC tumor progression and decreases at stage 4 after initial growth relative to normal tissues." (PMID 34046336, 2021). "Therefore, increased BHLHE41 expression leads to an increase in the proliferative properties of tumor cells at the initial stage of ccRCC development." (PMID 34046336, 2021). "Therefore, the contribution of BHLHE41 to tumor progression remains controversial and possibly depends on the tumor origin or stage." (PMID 31487856, 2019). "To investigate further how BHLHE41 overexpression could promote tumour growth, we performed RNA-seq on ACHN-BHLHE41 and ACHN-vector cells." (PMID 27384883, 2016). "In the TCGA samples, overexpression of BHLHE41 in tumour is specific to RCC." (PMID 27384883, 2016). "In addition, the IHC assay demonstrated that BHLHE41 was also overexpressed in tumor tissues." (PMID 35615737, 2022). "The results demonstrated that the overexpression of BHLHE41 significantly decreased the levels of N-cadherin, vimentin, and MMP9 and significantly increased the level of E-cadherin in tumor tissue (P < 0.01)." (PMID 35615737, 2022). "Hence, based on the construction of a hypoxia-induced CC cell model in vitro and a CC tumor xenografts model in vivo, this study was aimed at exploring that whether BHLHE41 overexpression could alleviate the malignant behavior of hypoxia-induced CC by regulating the HIF-1α/EMT pathway." (PMID 35615737, 2022). "In human tumor cells, there are functional differences in their roles: BHLHE40 induces apoptosis and epithelial-mesenchymal transition (EMT), whereas BHLHE41 inhibits them." (PMID 36412639, 2022). "The expression of the IGFBP3 gene is coordinated with BHLHE41 as well as with other HIF-1α-activated genes, decreasing in expression as the tumor grows." (PMID 34046336, 2021). "The first group included CA9, NDUFA4L2, EGLN3, BHLHE41, VWF, IGFBP3, and ANGPTL4, whose expression levels were coordinately decreased during tumor progression." (PMID 34046336, 2021). "In the stages after initial growth, the downregulation of BHLHE41 helps to create conditions for EMT and the invasion of tumor cells." (PMID 34046336, 2021). "Increased expression of BHLHE41 led to the inhibition of EMT in vitro, as well as tumor growth and in vivo metastasis." (PMID 31936274, 2020).
tumor (continued). "We did not observe an association between BHLHE41 mRNA expression levels and adverse pathologic factors: Fuhrman grade (Wald test P value=0.88), metastasis (Wald test P value=0.8), node involvement (Wald test P value=0.72) or tumour stage (Wald test P value=0.51)." (PMID 27384883, 2016). "Hypoxia has been shown to be a potent inducer of tumor dormancy, for example, via the upregulation of the transcription factor NR2F1 and of the dormancy genes CDKN1B and DEC2 (also known as basic helix-loop-helix family member E41) in patient-derived and transgenic mouse models." (PMID 35837334, 2022). "We demonstrate for the first time that the expression of the genes CA9, NDUFA4L2, EGLN3, BHLHE41, IGFBP3, and ANGPTL4, regulated by HIF1, is largely correlated, and along with VWF, the expression levels of these genes during tumor progression decreased coordinately." (PMID 34046336, 2021). "After blocking MAPK‐JNK signalling pathway by an inhibitor, we found that BHLHE41 silencing by siRNA failed to promote tumour cell invasion." (PMID 32073238, 2020). "After blocking the MAPK/JNK signalling pathway by specific inhibitor SP600125, silencing of BHLHE41 failed to promote tumour cell invasion." (PMID 32073238, 2020). "The transcription factors include NR2F1/COUPTF173,74, BHLHE41/Dec2/Sharp-114,73 and FOXM172,73, which may serve as a “switch” for converting active tumor cells into “dormant” cells." (PMID 31819067, 2019). "First, the expression of BHLHE41 is increased in ccRCC tumours, not decreased as is the case for TNBC." (PMID 27384883, 2016). "In an analysis of TCGA RCC tumours, we observed marked overexpression of BHLHE41, but not in breast, lung, colon or other cancers." (PMID 27384883, 2016). "We did not see higher BHLHE41 expression in tumours from bladder, breast, colon, head/neck, liver, lung, pancreas or prostate." (PMID 27384883, 2016). "In TNBC cells, BHLHE41/DEC2 can bind and inhibit HIF-1α and HIF-2α functions by promoting their proteasomal degradation that is independent of the von Hippel–Lindau tumor suppressor, which is an E3 ligase of HIF-1α and HIF-2α proteins, and suppress tumor invasion and metastasis in an in vivo model." (PMID 37511489, 2023). "So as these genes—CA9, NDUFA4L2, BHLHE41, and EGLN3—are HIF-1α-regulated, from the standpoint of the metastasis biology, a decrease in their expression might suggest a transition of tumor cells to a more malignant condition after an adaptation process that might provoke metastases." (PMID 31936274, 2020). "On the other hand, it has been shown that decreased HIF-1α expression, due to up-regulation of a basic helix-loop-helix (bHLH) transcriptional repressor (SHARP1, bHLHE41 or DEC2), may inhibit tumor growth and angiogenesis via a negative regulation of VEGF expression." (PMID 27126599, 2016). "Furthermore, METTL3 upregulates basic helix-loop-helix family member E41 (BHLHE41) expression, which subsequently induces CXCL1 transcription in the inflammatory TME, enriching inflammatory factors and recruiting myeloid-derived suppressor cells (MDSCs) to suppress tumor-specific immune response." (PMID 40986143, 2025).